FOLH1 (folate hydrolase 1)
Description:
Has both folate hydrolase and N-acetylated-alpha-linked-acidic dipeptidase (NAALADase) activity. Has a preference for tri-alpha-glutamate peptides. In the intestine, required for the uptake of folate. In the brain, modulates excitatory neurotransmission through the hydrolysis of the neuropeptide, N-aceylaspartylglutamate (NAAG), thereby releasing glutamate. Involved in prostate tumor progression. Also exhibits a dipeptidyl-peptidase IV type activity. In vitro, cleaves Gly-Pro-AMC.
Synonyms: FGCP; GCPII; mGCP; PSM; PSMA; FOLH; NAALAD1; NAALAdase; GCP2
Tractability: Small molecule: an approved drug acts on it; a structure with a bound ligand is known; a high-quality ligand is known; it has a high-quality binding pocket; it belongs to a druggable protein family. Antibody: a drug acting on it is in phase 2 or 3 trials; UniProt places it where antibodies can reach, with high confidence; its Gene Ontology location is reachable by antibodies, with high confidence; UniProt predicts a signal peptide or a membrane-spanning region. PROTAC: a small molecule that binds it is known. Other modalities: a drug acting on it is in phase 2 or 3 trials.
Target class: Metallo protease M28 family; Enzyme; Protease; Metallo protease; Metallo protease MH clan; Metallo protease M28B subfamily
Safety:
Unwanted effects reported when the protein is acted on. In parentheses: how it was acted on, where the effect was seen, and who reports it.
hematological toxicity (source: ClinPGx)
Gene: Protein-coding gene on chromosome 11 (49,145,092 to 49,208,640, reverse strand). Ensembl gene ENSG00000086205.
Subcellular location: Cell membrane; Cytoplasm (Isoform PSMA')
Pathways (Reactome):
Metabolism: Aspartate and asparagine metabolism
Gene Ontology:
Molecular function: Ac-Asp-Glu binding; metallocarboxypeptidase activity; tetrahydrofolyl-poly(glutamate) polymer binding; peptidase activity; carboxypeptidase activity; dipeptidase activity
Biological process: intestinal folate absorption; L-glutamate biosynthetic process; proteolysis; positive regulation of glutamate receptor signaling pathway
Cellular component: cell surface; cytoplasm; extracellular exosome; plasma membrane; membrane
Genetic constraint (gnomAD): Loss-of-function variants: 43 observed, 69.22 expected, observed/expected ratio (o/e) 0.62, 90% interval 0.49 to 0.8. The upper end of that interval is the gene's LOEUF score, 0.8, which puts it in group 3 of 6, group 1 being the genes least tolerant of losing a copy. Missense variants: 502 observed, 755.01 expected, observed/expected ratio (o/e) 0.66, 90% interval 0.62 to 0.72. Synonymous variants: 215 observed, 260.32 expected, observed/expected ratio (o/e) 0.83, 90% interval 0.74 to 0.93.
Homologues: Orthologues: chimpanzee FOLH1 (99% identical), macaque FOLH1 (97% identical), dog FOLH1B (91% identical), pig FOLH1B (91% identical), guinea pig FOLH1 (90% identical), rabbit FOLH1 (85% identical), mouse Folh1 (85% identical), rat Folh1 (85% identical), tropical clawed frog naalad2 (68% identical), zebrafish naalad2 (66% identical), Caenorhabditis elegans gcp-2.1 (32% identical), Caenorhabditis elegans gcp-2.2 (31% identical). Paralogues in human: NAALAD2 (68% identical), NAALADL1 (37% identical), TFR2 (25% identical), TFRC (25% identical), NAALADL2 (23% identical).
Diseases named in the same sentence as FOLH1 in open-access papers:
FOLH1 is named in the same sentence as 372 diseases in open-access papers, as found by Europe PMC text mining. Sharing a sentence is not in itself a finding about the gene and the disease. The quoted sentences say what the papers report.
prostate carcinoma (2,982 papers, 2002 to 2026). A carcinoma that arises from epithelial cells of the prostate gland. "Prostate-specific membrane antigen (PSMA) is a type II transmembrane glycoprotein encoded by the folate hydrolase 1 (FOLH1) gene, which is highly expressed in prostate cancer cells." (PMID 40123907, 2025). "This transmembrane glycoprotein, encoded by the FOLH1 gene, is highly enriched in prostate cancer ­compared to healthy or benign tissue." (PMID 41056440, 2025). "PSMA is a type II transmembrane glycoprotein encoded by the FOLH1 (Folate hydrolase) gene and was first found as the target for monoclonal antibody 7EII-C5.3 in a preclinical study with prostate cancer cell lines." (PMID 35407435, 2022). "Prostate-specific membrane antigen (PSMA) is a transmembrane protein that is encoded by the FOLH1 (folate hydrolase 1) gene and was first discovered in prostate cancer cells." (PMID 34120192, 2021). "Prostate-specific membrane antigen is a type II transmembrane glycoprotein encoded by the FOLH1 gene that was initially found expressed highly on prostate cancer cells but is also expressed in the tumour-related neovasculature of several other malignancies including RCC." (PMID 39335784, 2024). "Prostate-specific membrane antigen (PSMA), also known as glutamate carboxypeptidase II, N-acetyl-L-aspartyl-L-glutamate peptidase I and folate hydrolase 1, is a transmembrane enzyme that is highly expressed on prostate cancer cells and in tumor-associated neovasculature of other cancers." (PMID 36168623, 2022). "Collectively, these findings enhance our understanding of the role of FOLH1/PSMA in prostate cancer biology and its potential as a multifaceted molecular indicator to inform prognosis and therapeutic strategies in prostate cancer." (PMID 41056440, 2025). "To begin to explore the predictive value of FOLH1 expression in the entire adenocarcinoma prostate cancer cohort, we analyzed treatment outcomes for patients receiving lutetium 177Lu-PSMA-617 (n = 149)." (PMID 41056440, 2025). "Transcripts of prostate cancer-associated biomarkers—kallikrein-related peptidase-2 and -3 (KLK2, KLK3), folate hydrolase 1 (FOLH1), and neuropeptide Y (NPY)—were detected in the platelets of cancer patients but not in those of healthy controls." (PMID 40332071, 2025). "For high-grade prostate cancer (HG-PCa), the smMIP-method identified 8 markers, and the microarray identified 17 markers, with FOLH1, FAP and CLDN3 being common across both platforms." (PMID 39595976, 2024). "PSMA (FOLH1) expression is reported to be suppressed in prostate cancer following neuroendocrine differentiation." (PMID 37628903, 2023). "One of the molecular targets used for the visualization of prostate cancer is PSMA (also known as glutamate carboxypeptidase II, folate hydrolase 1, N-acetylated α-linked acidic dipeptidase, or N-acetyl-L-aspartyl-L-glutamate peptidase)." (PMID 38139219, 2023). "For example, prostate specific membrane antigen or glutamate carboxypeptidase 2 (FOLH1/PSMA) was identified by sBioSITe as a cell surface protein and it is a well characterized diagnostic and potential therapeutic target in prostate cancer." (PMID 38053024, 2023). "For example, the prostate-cancer-specific biomarker FOLH1 has been found on prostate-derived exosomes and EGFR protein has been validated as an exosomal component for NSCLC cell lines with high expression of EGFR." (PMID 36768152, 2023). "Prostate-specific membrane antigen (PSMA), a transmembrane protein encoded by the gene FOLH1, is a relatively novel target for molecular imaging and therapy in prostate cancer imaging." (PMID 36766670, 2023). "Prostate-specific membrane antigen (PSMA) is an essential molecular regulator of prostate cancer (PCa) progression coded by the FOLH1 gene." (PMID 35162969, 2022). "Prostate-specific membrane antigen (PSMA), also known as glutamate carboxypeptidase II or folate hydrolase 1, is found to be overexpressed in prostate carcinoma epithelium." (PMID 36476583, 2022).
prostate carcinoma (continued). "FOLH1/PSMA has been widely studied in prostate cancer as a theranostic target, and its expression is suggested to increase upon ADT." (PMID 35345457, 2022). "GCPII is known by many other names, including folate hydrolase (thus encoding by the FOLH1 gene), and prostate-specific membrane antigen (PSMA), due to its high levels of expression in the prostate, with increased expression in prostate cancer." (PMID 35732693, 2022). "Prostate specific membrane antigen (PSMA), also known as folate hydrolase 1 (FOLH1) or glutamate carboxypeptidase II, is a type II transmembrane glycoprotein extensively studied in prostate cancers." (PMID 36367894, 2022). "Prostate-specific membrane antigen (PSMA, encoded by FOLH1) is upregulated in most prostate cancers and utilised as a therapeutic and diagnostic target." (PMID 36243890, 2022). "It is known from preclinical research that PSMA expression in prostate cancer cells is inversely modulated by the AR-signaling cascade, eventually involving the FOLH1 gene, which encodes PSMA." (PMID 35406467, 2022). "Prostate-specific membrane antigen (PSMA), also known as glutamate carboxypeptidase type II, is a transmembrane protein encoded by the gene FOLH1, firstly discovered in prostate cancer cells in 1987." (PMID 36355540, 2022). "PSMA is a trans membrane protein encoded by the gene FOLH1 and was first discovered in prostate cancer cells in 1987." (PMID 36011032, 2022). "The last targeted thorium-227 conjugate reported was towards PSMA or more specifically, glutamate carboxypeptidase II (GPCII) regulated by folate hydrolase 1 (FOLH1) gene and specific of prostate cancer cells (including in mCRPC)." (PMID 34207408, 2021). "Prostate cancer cells express prostate-specific membrane antigen (PSMA), a Glu carboxypeptidase II, also called folate hydrolase-1, which hydrolyzes Glu from vitamin B9 (folic acid) and other substrates." (PMID 32973771, 2020). "Prostate-specific membrane antigen (PSMA) or folate hydrolase 1 (FOLH1) is overexpressed in prostate cancer, and correlates with the PI3K/Akt signaling in cells." (PMID 32915913, 2020). "Another biomarker for prostate cancer is prostate-specific membrane antigen (PSMA), which is a membrane-bound zinc protease encoded by the FOLH1 gene, shown to be a marker for a type of aggressive prostate cancer cells." (PMID 30631980, 2019). "Another promising target for treating prostate cancer bone metastasis is folate hydrolase 1 (FOLH1; also known as prostate-specific membrane antigen [PMSA])." (PMID 31753020, 2019). "FOLH1, also known as PMSA (prostate-specific membrane antigen), is overexpressed in prostate cancer and is negatively regulated by androgen." (PMID 24252472, 2014). "Prostate-specific marker, FOLH1 (PSMA) was also detected in post-DRE Vn96-precipitated EVs from the urine of prostate cancer subjects." (PMID 25329303, 2014). "This enhanced understanding of the distinct molecular and clinical profiles of FOLH1-expressing prostate cancers may inform optimization of PSMA-directed treatments." (PMID 41056440, 2025). "It is also known as folate hydrolase 1 (FOLH1), glutamate carboxypeptidase II (GCPII), or N-acetyl-α-linked acidic dipeptidase I. PSMA is highly overexpressed in more than 85% of patients with prostate cancer." (PMID 40005958, 2025). "In this analysis of FOLH1 gene expression in 7,082 prostate cancer specimens, we detected highly stratified expression between primary tumors and various metastatic tumor sites, with lymph node having the highest expression and liver having the lowest expression compared to primary sites." (PMID 41056440, 2025). "Prostate-specific membrane antigen (PSMA) is a type 2 transmembrane protein that is encoded by the FOLH1 (folate hydrolase 1) gene and is overexpressed not only in prostate cancer cells but also in the neo-vasculature of several solid tumours such as breast cancer." (PMID 39355052, 2023).
prostate carcinoma (continued). "Prostate-specific membrane antigen (PSMA, also known as glutamate carboxypeptidase II, N-acetyl-L-aspartyl-L-glutamate peptidase I, and folate hydrolase 1) is a type II transmembrane glycoprotein acting as carboxypeptidase, highly expressed in prostate- and prostate cancer tissue." (PMID 33760944, 2021). "The FOLH1 gene was originally identified as a prostate specific membrane antigen detected as upregulated in prostate carcinoma, however expression of FOLH1 has since been observed in other tissues including the small intestine, particularly in the duodenal mucosa, the nervous system and the kidney." (PMID 22606341, 2012). "Indeed, the gene encoding PSMA is the folate hydrolase 1 (FOLH1) which is androgen-repressed; castration-resistant prostate cancer is potentially more radioresistant than HSPC due to persistent androgen receptor signaling, which leads to the upregulation of AR-regulated DNA repair genes." (PMID 39934300, 2025). "Also called folate hydrolase 1, it is highly over-expressed in prostate cancer cells, including castration-resistant prostate cancer, even when staining for prostate-specific antigen is negative; it is transferred to the luminal surface of the prostatic ducts upon malignant transformation." (PMID 30841602, 2019). "In another study where authors mined TCGA data, isolating 319 prostate-cancer DEGs enriched in xenobiotic-metabolism pathways, network analysis pinpointed AMACR, FOLH1, and NPY as core hubs." (PMID 40806607, 2025). "Overall, these data point to distinct epigenetic mechanisms of dysregulation of key prostate cancer biomarkers (GSTP1) including NE (ASCL1, SEZ6L), and luminal (e.g FOLH1) genes." (PMID 40593552, 2025). "Prostate-specific membrane antigen (PSMA; FOLH1) is a cell-surface target for diagnostics and treatment in prostate cancer." (PMID 41056440, 2025). "From these datasets, we extracted gene expressions, including FOLH1, GRPR, FAP, and Harris Hypoxia, and estimated the proportions of different cell types—epithelial, endothelial, and prostate cancer (PC) cells—in the corresponding ST spots." (PMID 39629134, 2024). "Other targets seem to be specific for prostate cancer, for instance, PSA (official symbol KLK3 [P07288]), PSMA (official symbol FOLH1 [Q04609]), and PSCA [O43653]." (PMID 39595075, 2024). "The prostate-specific membrane antigen (PSMA; also known as glutamate-carboxypeptidase II—GCPII; NAALADase; folate hydrolase I—FOLH1) has been widely studied as a drug target for prostate cancer imaging and therapy." (PMID 38177950, 2024). "PSMA, also known as folate hydrolase I (FOLH1) and glutamate carboxypeptidase II (GCPII), is a 750-aminoacid type II transmembrane glycoprotein which is 1000-fold overexpressed on the surface of prostate cancer cells." (PMID 36186578, 2022). "We found that the prostate cancer-specific genes, including KLK3, KLK2, FOLH1, and ACPP, are expressed mainly in luminal cells." (PMID 36712886, 2022). "The clusters isolated from the first patient expressed AR, KLK3 (PSA), or FOLH1(PSMA), displaying a profile similar to androgen-responsive LNCaP cells sequenced as one of the positive controls for prostate cancer cells." (PMID 35697674, 2022). "Folate hydrolase 1 (FOLH1) or prostate-specific membrane antigen (PSMA) is overexpressed in both IBD and prostate cancer." (PMID 35144655, 2022). "The prostate-specific membrane antigen (PSMA), also known as glutamate carboxypeptidase II (GCPII) or folate hydrolase 1 (FOLH1), is one of the cell-surface proteins overexpressed in prostate cancer." (PMID 33668474, 2021). "PSMA, also known as folate hydrolase 1 (FOLH1) or glutamate carboxypeptidase II (GCPII), is one of the proteins overexpressed on the surface of prostate carcinoma cells." (PMID 34069003, 2021).
prostate carcinoma (continued). "The reference-free diagnostic panel used the ratio of relative expression of three mRNAs that are overexpressed (FOLH1, XBP1 and HPN) to five mRNAs that are underexpressed (ITSN1, GSTM4, LTBP4, NELL2, and CFD) in prostate cancer compared to normal tissue." (PMID 33172003, 2020). "For prostate cancer, prostate-specific membrane antigen (PSMA, also known as folate hydrolase-1) is the most validated theragnostic target to date." (PMID 32257692, 2020). "In contrast, the expression of the prostate cancer marker genes KLK3 (p < 0.01), FOLH1 (p < 0.05), and PSCA (p < 0.05) was decreased in CTCs at CRPC relapse." (PMID 31877738, 2019). "It is important to note that well known prostate cancer biomarkers including PSA, FOLH1/PMSA, TGM4, and TMPRSS were also found to be enriched in urinary exosomes from prostate cancer patients compared to controls." (PMID 26196085, 2015). "Folate hydrolase 1, also known as prostate-specific membrane antigen, and KLK2 have been studied as prostate cancer serum biomarkers." (PMID 22515324, 2012). "The list of 10 genes again included the well-established prostate cancer markers KLK2, KLK3 (PSA), FOLH1 (PSMA), PSGR (OR51E2), STEAP2, NKX3.1 and Prostein), and also included NCAM2, SPON2 and HOXB13." (PMID 15583692, 2005). "In this regard, transcripts of prostate cancer biomarkers, including kallikrein-related peptidase-2 and −3 (KLK2, KLK3), folate hydrolase 1 (FOLH1), and neuropeptide-Y (NPY), were found exclusively in the platelet fraction of cancer patients and were absent in healthy controls." (PMID 39934930, 2025). "Although PSMA-targeted imaging has been very effective in detection of PSMA expressing tumors, prostate cancers with neuroendocrine differentiation do not express PSMA due to FOLH1 gene suppression and thus, making this imaging technique ineffective." (PMID 37493837, 2023). "Surely, one of the most well-known and clinically validated markers of prostate cancer is the prostate-specific membrane antigen (PSMA, also known as folate-hydrolase 1), a 100 kD transmembrane glycoprotein with expression properties that allow its use as diagnostic and therapeutic target." (PMID 33557050, 2021). "FOLH1 which controls PSMA expression is notably not upregulated in these samples and suggests that alpha particle therapeutics targeting PSMA expressed on prostate cancer (e.g., J591 or PSMA-617) will not engage a similar feed-forward mechanism." (PMID 29691406, 2018). "Importantly, well characterized prostate cancer related proteins such as PSA and FOLH1/PSMA were also readily detected at higher level in the exosomes from patient samples." (PMID 26196085, 2015). "FOLH1 is an established biomarker for prostate cancer, but has not been previously identified as a biomarker for Crohn's disease." (PMID 22606341, 2012). "Interestingly, prostate-specific membrane antigen (PSMA, also called FOLH1), a glutamate carboxypeptidase, is also involved in glutamate metabolism and has been proven to influence the progression and metastasis of prostate cancer." (PMID 37904122, 2023). "EVs from individuals with prostate cancer typically include cancer-related proteins such as CD9, CD81, and TSG101, as well as Annexin A2, Fatty Acid Synthase (FASN), and a prostate cancer-specific biomarker termed FOLH1 (Prostate Specific Membrane Antigen or PSMA)." (PMID 36059497, 2022). "PSMA is coded by FOLH1, a gene located at chromosome 11 in a region that is not commonly deleted in prostate cancer." (PMID 36008950, 2022).
metastatic disease (292 papers, 2009 to 2026). "T regulatory cells (Tregs) and CD8+ T cells were also significantly depleted in FOLH1-High primary prostate tumors, lymph node metastases, and other metastatic tumors, while natural killer cells were slightly elevated (q < 0.0001)." (PMID 41056440, 2025). "Patients with metastatic tumors with high FOLH1 expression also had improved prognosis and modestly improved benefit from 177Lu-PSMA-617." (PMID 41056440, 2025). "Our study suggests that high FOLH1 expression may be associated with improved OS in both primary and metastatic prostate cancer including liver and bladder metastases but not for patients with certain metastatic tumors such as bone and lung." (PMID 41056440, 2025).
metastatic prostate carcinoma (239 papers, 2012 to 2026). A carcinoma that arises from the prostate gland and has spread to other anatomic sites. "B7-H3(CD276), PSMA(FOLH1) and STEAP1 are co-expressed in metastatic prostate cancers." (PMID 40964329, 2025).